FASLG (Fas ligand)
Diseases named in the same sentence as FASLG in open-access papers (continued):
Sharing a sentence is not in itself a finding about the gene and the disease.
colorectal cancer (32 papers, 1999 to 2026). A primary or metastatic malignant neoplasm that affects the colon or rectum. "The tyrosine phosphorylation turns off the proapoptotic signal and turns on the pro-survival signals that lead to colorectal cancer cell proliferation and migration induced by its ligand, Fas ligand (FasL/TNFSF6/CD95L)." (PMID 30127519, 2018). "High FASLG expression in the CRC patients complies with previous clinical observations in which high FASLG expression was correlated with high incidences of metastases and poor survival in colorectal carcinoma patients and in other carcinoma patients." (PMID 22496728, 2012). "Most data on the therapeutic potential of tumour necrosis factor-related apoptosis-inducing ligand (TRAIL) as well as resistance to FAS ligand (FASL) in colorectal cancer have come from in vitro studies using cell lines." (PMID 17551494, 2007). "Furthermore, several studies claimed that decreased FASLG expression affected cell apoptosis and proliferation among different cancers such as breast and colorectal cancer and hepatocellular." (PMID 31416448, 2019). "Colorectal carcinoma cells have recently been shown to express Fas ligand (FasL)." (PMID 10098769, 1999). "For this reason, we screened 7 m6A-related genes (IL12RB1, FASLG, CXCL13, GBP2, CXCL10, CXCR6, and CIITA) through WGCNA and LASSO regression in this study and established an m6A-GPI in colorectal cancer." (PMID 37427112, 2023). "In colorectal cancer cells, EA induces the expressions of TNFR, Fas ligand, and FasR to activate intrinsic and extrinsic apoptosis pathways." (PMID 36675019, 2023). "We showed that upon coculture with colorectal cancer cells, peripheral and intestinal iNKT cells expressed TRAIL, Fas ligand, and released granzyme B and perforin." (PMID 34535957, 2021).
diabetes (32 papers, 2007 to 2026). "Fas/Fas ligand system was shown to be related to insulin resistance and type 2 diabetes mellitus (T2DM)." (PMID 30024959, 2018). "Other validated target of miR-21 are the fas ligand (Faslg), Pdcd4, and Tiam1 which are also related to diabetes." (PMID 25671565, 2015). "Moreover, inflammatory conditions promote activation of apoptotic pathways, including Fas ligand (FasL) signalling, which contributes to accelerated β‐cell death and disease progression in diabetes." (PMID 41549047, 2026). "One study has revealed that reduced T cell Fas ligand expression prevents diabetes in NOD mice, and several similar studies have focused on the importance of Fas in beta cell death and the development of diabetes, although evidence against a role of Fas has also been presented." (PMID 21816064, 2011). "The free energy of the interaction of miR-466 and ID00436.3p-miR with mRNA of the BACH2, FASLG, HEMGN and IGF2R genes, which are involved in diabetes diseases, is −105 ± 1 kJ/mole with GU repeats in the 3′UTR." (PMID 35627185, 2022). "There was one notable interaction between INS genotype and T1D status, however, in which antigen-specific T cells from control subjects with the diabetes-protective proinsulin VNTR III preferentially expressed IL-10, IL-2, and FASLG, genes known to participate in potent regulatory pathways." (PMID 24844227, 2014). "However, the role of soluble Fas ligand (sFasL) in functioning of immune cells in type 2 diabetes mellitus (T2DM) has not been studied yet." (PMID 30024959, 2018).
Sepsis (30 papers, 2009 to 2026). Sepsis is defined as life-threatening organ dysfunction caused by a dysregulated host response to infection. "This is supported by the findings of a previous study revealing that the plasma level of the Fas ligand (FasL), a trigger of necroptosis, was associated with the severity of sepsis and was predictive of mortality." (PMID 40318009, 2025). "In a prospective cohort enrolled septic patients, there was a significant difference in 90-day mortality between low and high serum concentrations of FASLG, further, we provided the novel results of diagnostic value of FASLG for sepsis." (PMID 38894720, 2024). "sFas, Fas ligand, and their ratio were associated with a high sepsis-related organ failure assessment (SOFA) score in patients with bacteremia." (PMID 37342494, 2023). "The stored blood samples were estimated for TNF-α, A Disintegrin and Metalloproteinase Motifs 13 (ADAMTS13), and soluble Fas ligand (FasL) at the end of the study to confirm the biomarker-based inflammatory phenotypes of sepsis-induced MOFS." (PMID 41883885, 2026). "In the GSE13904 dataset, the expression trends of BCL2 and FASLG showed a significant decrease in sepsis, while JAK3 exhibited elevation." (PMID 38894720, 2024). "In summary, we systematically identified 11 apoptosis-related differentially expressed genes in sepsis, and four hub genes (BCL2, FASLG, JAK3 and IRF9) were recognized as valuable diagnostic biomarkers." (PMID 38894720, 2024). "During sepsis, casp-8 can be activated by signaling complex via death receptors, like FAS ligand or TNF-α." (PMID 35190789, 2022). "In sepsis, endotoxin stimulates the synthesis and release of various pro-inflammatory cytokines and factors, including TNFα, IL-1β, IL-6, Fas ligand (FasL), granzymes, etc., mainly by mononuclear macrophages." (PMID 32457606, 2020). "Programmed cell death of T-cells in sepsis is mediated by a number of stimuli (e.g. Fas ligand, TNF-α or steroids) and can proceed via different apoptotic pathways." (PMID 19740426, 2009). "Apoptosis in renal cells occurs through TNF-α and Fas ligand-mediated pathways during sepsis." (PMID 23476127, 2013). "Apoptosis can be induced via both the extrinsic (TNF-α, Fas ligand) and intrinsic pathways (mitochondrial) during sepsis, and prevention of lymphoid cell apoptosis could markedly attenuate parameters of sepsis and improve survival." (PMID 23233853, 2012). "Thus, it is highly likely that FASLG is involved in the regulation of immune response in sepsis." (PMID 38894720, 2024). "However, C5a exposure alone could not stimulate normal thymocyte apoptosis, suggesting that other factors such as TNF-α and Fas ligand-induced by sepsis were indispensible for C5-indued apoptotic death of thymocytes." (PMID 23233853, 2012). "The volcano plot and heatmap indicated that JAK3, CHMP5 and IFNAR1 were upregulated while CASP8, VDAC2, FASLG, JAK1, STAT4 and BCL2 were downregulated in sepsis." (PMID 38894720, 2024). "BCL2, FASLG, IRF9 and JAK3 might be key regulatory genes affecting apoptosis in sepsis." (PMID 38894720, 2024).
pancreatic cancer (27 papers, 2005 to 2025). "Many studies have reported that FAS expression is aberrant in various pancreatic tumours while FASLG is seen in both normal pancreatic cells and pancreatic neoplasia." (PMID 32606315, 2020). "As CHST11 is a key enzyme for glycosaminoglycan sulfation, these results suggest CHST11+ naive T cells in pancreatic cancer may have "Th2 differentiation tendency" and promote T cell exhaustion by enhancing apoptosis sensitivity via the FAS/FASLG pathway." (PMID 41346619, 2025). "Compounding this challenge, the pancreatic tumor cells themselves produce and release potent immunosuppressive agents, such as Transforming Growth Factor-beta (TGF-β), Interleukin-10 (IL-10), Interleukin-6 (IL-6), Vascular Endothelial Growth Factor (VEGF), and the Fas ligand." (PMID 37958483, 2023).
cervical carcinoma (26 papers, 2000 to 2025). A carcinoma arising from either the exocervical squamous epithelium or the endocervical glandular epithelium. "Polymorphisms in the Fas (FasR) and Fas ligand (FasL) genes have been reported to be associated with cervical cancer in certain populations." (PMID 19941645, 2009). "FASLG may be a candidate signature for the mechanism of radiotherapy response in cervical cancer." (PMID 34414195, 2021). "Mechanistic studies reveal that thymic stromal lymphopoietin (TSLP) activates eosinophils that promote proliferation and survival of cervical cancer cells through upregulating Ki-67, proliferating cell nuclear antigen (PCNA) and BCL-2 and downregulating Fas and Fas ligand (FasL)." (PMID 34359674, 2021).
Hypertension (26 papers, 2014 to 2025). The presence of chronic increased pressure in the systemic arterial system. "In the regulation of apoptosis, exercise training downregulated the proapoptotic protein in hypertension by decreasing the upstream regulation of apoptosis such as the Fas ligand, TNF, TNF receptor 1, and FADD, and the downstream regulation of apoptosis such as t-Bid, Bad, Bak, and Bax." (PMID 37187789, 2023).
Hepatitis (25 papers, 2010 to 2024). Inflammation of the liver. "Therefore, Fas ligand and receptor interactions do not appear to provide an explanation for mild hepatitis symptoms in the HBV-s-rec strain." (PMID 38129531, 2023). "The mechanism of EBV hepatitis is thought to be that EBV infected and activated CD8 + T-cells accumulate in the liver and the products of the EBV-infected CD8 + T cells or infiltrating cytotoxic T lymphocytes were interferon-γ, tumor necrosis factor and Fas ligand, which can destroy hepatocytes." (PMID 35189820, 2022).
atherosclerosis (22 papers, 2007 to 2025). A disease characterized by the build-up of fatty material and calcium deposition in the arterial wall resulting in partial or complete occlusion of the arterial lumen. "The interactive role of Fas/Fas ligand in atherosclerosis has been studied by many researchers after it was established that both Fas and its receptor Fas ligand are indeed present in human atherosclerotic plaques." (PMID 26322329, 2015). "In IS, the overexpression of miR-21 could reverse the pathological processes of atherosclerosis, decrease the FASLG levels, and protect against ischemic neuronal death." (PMID 35173580, 2022). "Furthermore, in the process of human atherosclerosis, Fas ligand (FasL) which is a 40-kDa cytotoxic type II transmembrane protein from the TNF family, is expressed together with markers of apoptosis in inflammatory regions of plaques." (PMID 31781165, 2019).
colitis (22 papers, 2014 to 2024). Inflammation of the colon. "DPSCs induce apoptosis in activated T cells in vitro and reduce inflammatory tissue damage in mice with colitis, which is related to the expression of Fas ligand (FasL) by DPSCs." (PMID 36973490, 2023). "Mechanistically, ASA was capable of upregulating the expression of Fas ligand (FasL) in iGMSCs, leading to an improvement in iGMSC-mediated T cell apoptosis and therapeutic efficacy in the treatment in colitis mice." (PMID 31796122, 2019). "Fas ligand (FasL)-deficient mice-derived MSCs were not able to suppress disease in DSS-induced colitis models." (PMID 33171878, 2020). "MSCs ameliorate DSS-induced colitis by suppressing Th1/Th17 cell responses and inducing Treg cells either by direct or indirect actions through the induction of M2 macrophages, which is mediated by PGE2, TSG-6, and the Fas ligand." (PMID 38139314, 2023).
preeclampsia (22 papers, 2012 to 2025). Preeclampsia is a hypertensive disorder of pregnancy that is characterized by new-onset hypertension with proteinuria presenting after 20 weeks of gestation, and depending on mild or severe forms may initially present with severe headache, visual disturbances, and hyperreflexia. "Several studies investigated the association between various single-nucleotide polymorphisms (SNPs) in Fas and Fas ligand (FasL) genes and the risk of preeclampsia." (PMID 30718366, 2019). "Fas ligand (FasL) and cytochrome c expressions play roles in the apoptotic pathway in placental hypertension or preeclampsia (PE)." (PMID 34025182, 2021). "Intriguingly, only one among the 18 microarray studies observed that apoptosis-related genes, BAX, FASLG and p53AIP, were up-regulated in preeclampsia, in line with a previous study that genes coding for caspase-10, death-receptor 3 were altered." (PMID 22929622, 2012). "An increased Fas ligand in placental-derived extracellular vesicles of women with preeclampsia." (PMID 40698658, 2025). "Fas ligand expression and probably cytokine production by CD8+ T cells and NKT-like cells could still be regulated by the PD-1 mediated pathway in early-onset preeclampsia." (PMID 30700015, 2019). "Thus Fas ligand plays an important role in the maintenance of pregnancy, normal fetal development, but also in the pathophysiology of preeclampsia." (PMID 40698658, 2025).
lymphopenia (21 papers, 2015 to 2025). Reduction in the number of lymphocytes. "The reason for the development of lymphopenia remains unclear but potentially includes (i) the loss of lymphocytes as an immune-related hematological side effect, (ii) apoptosis triggered by Fas-ligand expressed within the tumor microenvironment, and (iii) apoptosis due to excessive exhaustion." (PMID 35805052, 2022). "Lymphopenia was also reported in patients with SARS-CoV as a result of the involvement of soluble vascular cell adhesion molecule-1 (sVCAM-1), soluble Fas ligand (sFasL), and glucocorticoids." (PMID 33445583, 2021). "It was reported that FASLG and TNFSF10 can trigger apoptosis in both CD4+ and CD8+ T cells, which could explain the lymphopenia during ASF infection." (PMID 31725732, 2019).
myeloma (21 papers, 2013 to 2025). "Intriguingly, normal cell-derived apoVs can induce multiple myeloma (MM) cell apoptosis and inhibit MM cell growth, using Fas ligand (FasL) to induce MM cell apoptosis via Fas pathway." (PMID 39872110, 2023). "A recent myeloma study suggests that using MSCs with high Fas ligand in multiple myeloma bearing mice increased apoptosis of the myeloma cells." (PMID 25054153, 2014). "The mechanisms of canopy disruption are not fully understood, but it may be mediated by cancer-induced apoptosis of the canopy cells, as myeloma cells have been shown to induce apoptosis in osteoblastic cells via tumor necrosis factor-related apoptosis-inducing ligand (TRAIL) and Fas-Ligand (FasL)." (PMID 38067289, 2023).
neuroblastoma (18 papers, 2009 to 2025). Neuroblastoma (NB) is the most common solid, extracranial childhood tumor. "The most highly mutated genes, such as MYC, TERT, FASLG, RIPK1, TNFSF10, TARDBP, and CDKN2A, have been well characterized in liver cancer, diffuse large B-cell lymphoma, neuroblastoma, and kidney renal clear cell carcinoma." (PMID 35875102, 2022). "We transfected the FLAG-tagged forms of FAIM-L, FAIM-S, FAIM-L-2a, and FAIM-S-2a into neuroblastoma derived cells and stimulated these cells with soluble Fas Ligand (sFasL)." (PMID 28981531, 2017).
pulmonary fibrosis (18 papers, 2005 to 2025). Chronic progressive interstitial lung disorder characterized by the replacement of the lung tissue by connective tissue, leading to progressive dyspnea, respiratory failure, or right heart failure. "A pathogenic role for macrophages in pulmonary fibrosis has been postulated for many years, and described mechanisms have included overexpression of reactive oxygen species, proteinase-activated receptors, Fas ligand, and profibrotic cytokines." (PMID 22824096, 2012). "Among them, FASLG plays a key role in pulmonary fibrosis by inducing inflammatory apoptosis in epithelial cells and alveolar macrophages, and its blockade can prevent or attenuate lung fibrosis." (PMID 36014018, 2022). "T cells can regulate the pulmonary fibrosis outcome through cAMP-regulated chloride channels, Fas-Fas ligand (FasL) interactions, or T cell exhaustion." (PMID 32676074, 2020).
osteosarcoma (17 papers, 2010 to 2025). A usually aggressive malignant bone-forming mesenchymal neoplasm, predominantly affecting adolescents and young adults. "Osteosarcoma primarily metastasizes to the lungs, where FAS ligand (FASL) is constitutively expressed." (PMID 37569529, 2023). "MSP-4 can help induce the apoptosis of MG63 cells through the Fas/Fas ligand (FasL)- and mitochondria-mediated pathways, suggesting that it may be used as an innovative alternative treatment against human osteosarcoma." (PMID 34409948, 2021).
Arthritis (16 papers, 2005 to 2025). Inflammation of a joint. "Moreover, CD5+ Fas ligand positive Breg cells were implicated in immune regulation in collagen-induced arthritis by promoting apoptosis in arthritis-associated T cells." (PMID 24945741, 2014). "The involvement of Fas and Fas ligand (FasL) has also been proposed in osteoblast differentiation, and confirmed in animal models of Fas deficiency, which is found to protect animals from osteoporosis and joint destruction in arthritis." (PMID 22687048, 2012). "Fas/Fas ligand system is considered to have a dual role in arthritis, inducing apoptotic cell death of hyperplastic synoviocytes and inflammatory cells, but also exerts proinflammatory effects." (PMID 40443734, 2025). "Death receptor (DR5) is a Fas-independent receptor for soluble Fas ligand (sFasL) that promotes arthritis." (PMID 34223817, 2021).
liver cancer (16 papers, 2005 to 2023). An epithelial or non-epithelial malignant neoplasm that arises from the liver. "The miRNA-21 was demonstrated to promote the proliferation, migration, and invasion of liver cancer cells through inhibiting FASLG, SOCS6, and KLF5." (PMID 37704828, 2023).
liver fibrosis (16 papers, 2012 to 2025). "However, further study is needed to explore the role of FASLG signaling pathway and CXCL and CCL signaling pathway(Cxcl16-Cxcr6, Ccl6-Ccr2 and Ccl5-Ccr5) in liver fibrosis of schistosomiasis." (PMID 36618421, 2022).
lupus nephritis (16 papers, 2008 to 2025). Glomerulonephritis in the context of systemic lupus erythematosus. "Fas ligand is also upregulated in the glomeruli and mesangial cells from human lupus glomerulonephritis." (PMID 18197980, 2008).
glaucoma (15 papers, 2011 to 2025). Increased pressure in the eyeball due to obstruction of the outflow of aqueous humor. "In the optic nerve of patients with glaucoma, elevated levels of both TNF-α and Fas ligand (FasL), a protein with proapoptotic capacity, are observed, and both are linked to the pathogenesis of glaucoma." (PMID 38333055, 2024). "TNF-α is found in the optic nerve in glaucoma patients and also Fas ligand (FasL), a proapoptotic protein, both being implicated in glaucoma pathogenesis." (PMID 33613418, 2020). "For example, immunization with HSP 27 or HSP60 in the Lewis rat induced a glaucoma-like pattern of RGC degeneration via activation of T cells which secreted Fas ligand." (PMID 23720653, 2013).